FHAD1 (forkhead associated phosphopeptide binding domain 1)
Description:
Regulator of sperm motility and spermatocyte meiosis.
Synonyms: KIAA1937
Tractability: No criterion of Open Targets' tractability assessment is met for any kind of drug.
Gene: Protein-coding gene on chromosome 1 (15,236,521 to 15,400,283, forward strand). Ensembl gene ENSG00000142621.
Subcellular location: Cell projection, cilium, flagellum
Subcellular location (Human Protein Atlas): Nuclear bodies; Nucleoplasm
Gene Ontology:
Cellular component: sperm flagellum; motile cilium
Genetic constraint (gnomAD): Loss-of-function variants: 126 observed, 163.19 expected, observed/expected ratio (o/e) 0.77, 90% interval 0.67 to 0.89. The upper end of that interval is the gene's LOEUF score, 0.89, which puts it in group 3 of 6, group 1 being the genes least tolerant of losing a copy. Missense variants: 1,510 observed, 1,706.7 expected, observed/expected ratio (o/e) 0.88, 90% interval 0.85 to 0.92. Synonymous variants: 581 observed, 651.21 expected, observed/expected ratio (o/e) 0.89, 90% interval 0.83 to 0.96.
Homologues: Orthologues: chimpanzee FHAD1 (92% identical), macaque FHAD1 (88% identical), pig FHAD1 (78% identical), dog FHAD1 (78% identical), guinea pig FHAD1 (69% identical), mouse Fhad1 (68% identical), rat Fhad1 (67% identical), rabbit FHAD1 (64% identical), zebrafish fhad1 (8% identical), zebrafish si:dkey-163f12.6 (5% identical). Paralogues in human: CCDC27 (6% identical).
Diseases named in the same sentence as FHAD1 in open-access papers:
FHAD1 is named in the same sentence as 4 diseases in open-access papers, as found by Europe PMC text mining. Sharing a sentence is not in itself a finding about the gene and the disease. The quoted sentences say what the papers report.
cervical cancer (1 paper, 2021). A primary or metastatic malignant neoplasm involving the cervix. "Based on Kaplan‐Meier analysis, PCBP1-AS1 and four mRNAs (FAM222A, FHAD1, WDR62, and SBK1) were identified as potential prognostic factors for cervical cancer patients." (PMID 33833992, 2021).
prostate carcinoma (1 paper, 2022). A carcinoma that arises from epithelial cells of the prostate gland. "Forkhead-associated domain-containing protein 1 (FHAD1) has been identified as a possible biomarker for prostate cancer." (PMID 36299731, 2022).
tumor (2 papers, 2017 to 2021). "The results showed that the expression of PCBP1-AS1, FAM222A, FHAD1, WDR62, and SBK1 was significantly correlated with tumor clinical stage, pathologic TNM, and lymphatic invasion (p < 0.05)." (PMID 33833992, 2021). "Quantitative polymerase chain reaction (qPCR) analysis revealed higher levels of SOX11, FHAD1, HORMAD1 and TFAP2B expression in DCIS‐SOX11 than in DCIS‐LacZ tumours." (PMID 28707729, 2017).
FHAD1 also shares sentences with these, for which no sentence is quoted: glioma (1 paper).